FBXW2 (F-box and WD repeat domain containing 2)
Diseases named in the same sentence as FBXW2 in open-access papers (continued):
Sharing a sentence is not in itself a finding about the gene and the disease.
metabolic disease (1 paper, 2020). A congenital disorder (due to inherited enzyme abnormality) or acquired (due to failure of a metabolically important organ) disorder resulting from an abnormal metabolic process. "To further investigate the underlying reasons of the positive effects of FBXW2 deficiency on metabolic disorders, we analyzed the inflammation condition in HFD‐fed myeloid FBXW2 deficiency mice." (PMID 33101872, 2020). "Importantly, FBXW2 deficiency‐mediated accumulation of KSRP dramatically disrupted the mRNA stability of several proinflammatory cytokines and chemokines, subsequently alleviating the inflammatory response and progression of metabolic diseases." (PMID 33101872, 2020).
FBXW2 also shares sentences with these, for which no sentence is quoted: breast tumor (1 paper); depression (1); hepatocellular carcinoma (1); Hyperinsulinemia (1); Insulin resistance (1); lymph-node metastasis (1); Marfan syndrome (1); triple-negative breast carcinoma (1).